IL1RN (interleukin 1 receptor antagonist)
Diseases named in the same sentence as IL1RN in open-access papers (continued):
Sharing a sentence is not in itself a finding about the gene and the disease.
asthma (continued). "The finding in the stratified analysis of IL1RN variants with odds ratios in opposite directions reinforces the importance of accounting for both environmental exposures and GEI in risk analyses for asthma." (PMID 32204425, 2020). "However, the GEI or differential association of childhood ETS exposure and risk for asthma or early onset asthma within various IL1RN genotype groups has not been reported." (PMID 32204425, 2020). "Although the uncommon rs2234678 SNP of the IL1RN gene is protective against the development of asthma in those without childhood tobacco exposure, those carrying this SNP with childhood environmental tobacco exposure, are at higher risk of early onset asthma." (PMID 36292755, 2022). "The divergent findings of an elevated risk for the interaction between IL1RN genotypes and childhood ETS for early onset asthma but not for asthma in the total population have precedent in the literature on childhood predisposition to asthma." (PMID 32204425, 2020). "Thus, the GEI between IL1RN tag SNPs and childhood ETS exposure for early-onset asthma is indeed significant in this study." (PMID 32204425, 2020).
atherosclerosis (9 papers, 2008 to 2025). A disease characterized by the build-up of fatty material and calcium deposition in the arterial wall resulting in partial or complete occlusion of the arterial lumen. "The ROC curve suggests that CD52 and IL1RN showed favorable diagnostic value in distinguishing between atherosclerosis and control data in the GSE43292, GSE97210, and GSE100927 datasets." (PMID 37173673, 2023). "A pro-inflammatory profile comprising SNPs in gene encoding regions of IL1B and IL1RN was further reported to confer an increased risk of atherosclerosis development and some studies have reported that IL1B and IL1RN polymorphisms are associated with genetic risk of IS." (PMID 31480765, 2019). "While this indicates that CD52 and IL1RN are highly expressed in foam cells, they still need to be further validated in vitro and in vivo to further explore their potential mechanisms in atherosclerosis." (PMID 37173673, 2023). "Results showed significantly increased expression of CD52 and IL1RN in ox-LDL-treated cells, suggesting that CD52 and IL1RN were induced in atherosclerosis cell models." (PMID 37173673, 2023). "One studies have shown that after in vitro and in vivo injection of endotoxin and LPS, six candidate genes (BATF, BID, C3aR1, IL1RN, SEC61B and SLC43A3) were identified to be associated with inflammation and atherosclerosis." (PMID 36303246, 2022). "Some studies have reported that IL1B:C(-31)T and IL1RN:VNTR polymorphisms are significantly correlated with the development of CAD, and thus atherosclerosis process." (PMID 31480765, 2019). "In addition, expression levels of CD52 and IL1RN in the atherosclerosis samples were also significantly higher than in the normal samples." (PMID 37173673, 2023). "Furthermore, by constructing a robust DEGs PPI network and integrating the 12 algorithms of cytoHubba, we identified two key genes, CD52 and IL1RN, and validated their performance in the diagnosis of atherosclerosis." (PMID 37173673, 2023). "​This study has established that CD52 and IL1RN may play a key role in the occurrence and development of atherosclerosis, which opens new lines of thought for further research on the pathogenesis of atherosclerosis." (PMID 37173673, 2023). "Interleukin-1 receptor antagonist (IL1RN) is a natural inhibitor of IL-1, and it has been reported that IL-1, primarily expressed in the endothelium of atherosclerotic plaques, is partly regulated by IL1RN and may be associated with the inflammatory mechanism of atherosclerosis formation." (PMID 34688276, 2021).
glioma (9 papers, 2015 to 2024). A benign or malignant brain and spinal cord tumor that arises from glial cells (astrocytes, oligodendrocytes, ependymal cells). "Our study of a single-cell dataset using the signaling pathway of the IL1RN gene showed that IL1RN expression in glioma-associated macrophages changes from low to high." (PMID 38594692, 2024). "When comparing glioma-associated macrophages/monocytes to naïve monocytes, only the expression of Il1rn, Tgfbi, and Cxcr4 was significantly higher." (PMID 25658639, 2015). "In murine gliomas at the asymptotic phase, MDMs upregulated Il-1b that encodes an inflammatory cytokine, along with genes encoding inflammatory cytokine inhibitors Il1rn and Il18, and there was a subset with a high expression of the Cd274 mRNA encoding an immune-checkpoint inhibitor (PD-L1)." (PMID 33809675, 2021). "In the GL261 model a significant higher expression of all selected genes could be confirmed in glioma-associated macrophages/monocytes and for Il1rn, Clec7a, and Cxcr4 in glioma-associated microglia, compared to the respective control cells." (PMID 25658639, 2015). "For example, cells deprived of methionine seem to suppress the expression of Interleukin 1 Receptor Antagonist (IL1RN), one of the main factors known to be upregulated in gliomas and suspected to promote the progression of the cell cycle in tumour cells." (PMID 39595047, 2024). "Using multiplex cytokine/chemokine analysis, these authors further demonstrated that nuclear IL-33 facilitates tumour growth by triggering glioma-mediated expression of inflammatory cytokines (LIF, IL-6, IL-8, IL-1RN, IL-1β and secreted IL-33." (PMID 36555253, 2022). "The pattern of TAM development in glioma started first with a microglia phenotype (P2RY12+/TMEM119+), then it turned to polarized macrophage (CD163+), and finally converged into M2b macrophages (IL1RN+) with activated expression of strong angiogenesis signaling molecules (VEGFA)." (PMID 34692159, 2020).
Obesity (9 papers, 2012 to 2026). Accumulation of substantial excess body fat. "Just as its murine counterpart, human IL1RN is reported to be associated with obesity, and variant rs4252041 C in the 3′ UTR and synonymous rs419598 C predispose Swedish men to higher total fat mass and body weight." (PMID 34834553, 2021). "When we analysed the association of the EQ-5D-3L usual activity dimension with sex, age, BMI, and genetic polymorphisms of IL-1R1 and IL-1RN, the EQ-5D-3L usual activity dimension had an association with older age (OR = 2.3, 95% CI: 1.2–4.5) and obesity (OR = 3.0, 95% CI: 1.1–8.0)." (PMID 37198429, 2023). "Interleukin-1 receptor antagonist (IL1RA) intron 2 86 bp repeat and interleukin-4 (IL4) intron 3 70 bp repeat are variable number tandem repeats (VNTRs) that have been associated with various diseases, but their role in obesity is elusive." (PMID 28293435, 2017).
colorectal cancer (8 papers, 2015 to 2025). A primary or metastatic malignant neoplasm that affects the colon or rectum. "In contrast, low levels of IL1RN have been associated with increased disease severity in myeloma, colorectal cancer and prostate cancer." (PMID 33238942, 2020). "IL-1RN rs4251961 was found to be associated with an increased risk of cancers e.g. colorectal cancer, but our study for the first time reports its association with an increased risk of NHL." (PMID 28060727, 2017). "Alloprevotella is notably enriched in tumors overexpressing IL23A and IL1RN genes, while Prevotellaceae_UCG‐001 is significantly more abundant in colorectal cancer mice." (PMID 39830908, 2025). "A sequencing of 338 cases of colorectal cancer showed that high-risk tumors exhibit high expression of the IL23A and IL1RN genes and are rich in bacteria such as Alloprevotella." (PMID 33816336, 2021).
coronary artery disease (8 papers, 2005 to 2024). "Notably, the polygenic analysis revealed that rs6734238 in the IL1F10/IL1RN locus was found to be significantly associated with coronary artery disease." (PMID 37382260, 2023). "IL1RN VNTR polymorphism has been widely implicated in ischemic stroke and coronary artery disease (CAD)." (PMID 26198819, 2015).
prostate carcinoma (8 papers, 2005 to 2025). A carcinoma that arises from epithelial cells of the prostate gland. "We found that CD11b-deficient, tumor-infiltrating leukocytes secrete IL1RN, which is crucial for tumor progression of prostate cancers." (PMID 33322099, 2020). "Further studies are needed to replicate our finding in other populations and to elucidate the biological function of the IL1RN haplotype in relation to prostate cancer risk." (PMID 16106254, 2005). "In summary, we found evidence of an association between a common haplotype in the IL1RN gene and prostate cancer in a Swedish population." (PMID 16106254, 2005). "In this study, we hypothesise that sequence variants in the IL1-RN gene are associated with prostate cancer risk." (PMID 16106254, 2005). "Implication of the IL1R1 and IL1RN genes directly implicates the gouty inflammation pathway in prostate cancer." (PMID 40385401, 2025). "LocusZoom plots were generated for each SNP that significantly contributed to the positive association between gout and prostate cancer, and each SNP was assigned to the closest gene: SLC30A5 (rs2560449), IL1R1 (rs17767183), IL1RN (rs9973741)." (PMID 40385401, 2025). "Although the tumor tissues contain a mixed population of cells (e.g., prostate cancer cells and immune cells), when comparing tumor tissues with their corresponding TILs, TILs showed increased expression of Il1rn (6–12 fold)." (PMID 32244522, 2020). "In light of earlier findings that in a Pten-null mouse prostate cancer model Gr1+CD11b+ leukocytes can secrete the IL1RN to overcome oncogene-induced senescence, we analyzed leukocytes prepared from either splenocytes or TRAMP-C1-derived tumors." (PMID 33322099, 2020). "CCL2 is involved in the malignant progression of prostate cancer, and the IL1RN was shown to increase the proliferation of normal prostate epithelial cells." (PMID 33322099, 2020). "Based on earlier studies using immunohistochemical analysis, IL1RN seems to have lower expression in prostate cancer samples compared with normal tissues." (PMID 32244522, 2020). "The aim of this study was to test for association of prostate cancer with sequence variants in the IL-1RN gene in a large population-based study in Sweden and in that way evaluate whether polymorphisms in a gene that regulates inflammatory processes might influence the risk of prostate cancer." (PMID 16106254, 2005). "In addition to CCL2, the C.M. collected from MSCs with the downregulation of IL1RN by the siRNA approach exhibited anti-proliferation activity against the prostate cancer cells." (PMID 36672395, 2023). "Based on our results, we propose a working hypothesis that prostate cancers recruit the TILs/CD11b− populations that secrete the IL1RN, which ameliorates the inflammatory stresses to androgen-sensitive cancers." (PMID 33322099, 2020). "Therefore, we concluded that TILs, not cancer cells, were the primary source for expressing and secreting IL1RN in the tumor microenvironment in the syngeneic prostate cancer model." (PMID 32244522, 2020). "Since two previously defined tumor-associated proinflammatory chemokines (CXCL1 and CCL2) were also detected in addition to the IL1RN, we asked whether there was a correlation in a human prostate cancer clinical dataset." (PMID 33322099, 2020). "Relatedly, sequence variants within the IL-1RN gene have been associated with various malignancies and infectious diseases, but the role of IL-1RN polymorphisms in prostate cancer pathogenesis has not been examined." (PMID 16106254, 2005). "Following the idea of anti-cancer function of IL1RN, we further compared the mRNA levels of IL1RN before ADT (pre-ADT) and after ADT (post-ADT, 22 weeks after ADT) in seven prostate cancer patients." (PMID 32244522, 2020). "Supporting this hypothesis, in an earlier study we once compared the mRNA levels of the IL1RN before ADT (pre-ADT) and after ADT (post-ADT, 22 weeks after ADT) in seven prostate cancer patients." (PMID 33322099, 2020).
prostate carcinoma (continued). "Since the IL1RN was involved in proliferation in the mouse TRAMP-C1 cell line, we further asked whether this effect is generally present in human prostate cancers." (PMID 33322099, 2020). "The IL1RN eQTL signal overlaps only with gout, and not with prostate cancer." (PMID 40385401, 2025). "However, when we analyzed gene expressions in several human prostate cancer datasets, the identified groups with higher mRNA levels of the three genes (IL1RN, CD11B, and CHIA) did not overlap (mRNA High)." (PMID 33322099, 2020). "Our MR study identified three genes driving the relationship between the non-hyperuricemia compartment of gout and prostate cancer: IL1R1 (rs17767183), IL1RN (rs9973741), and SLC30A5 (rs2560449)." (PMID 40385401, 2025).
osteoarthritis (7 papers, 2009 to 2023). A noninflammatory degenerative joint disease occurring chiefly in older persons, characterized by degeneration of the articular cartilage, hypertrophy of bone at the margins and changes in the synovial membrane. "Previous study reported the association of IL1RN with IL-1β in osteoarthritis, suggesting that the upregulation of IL1RN in σB transfected cell, can increase the occurrence of osteoarthritis." (PMID 29731966, 2018). "Two polymorphisms within Interleukin-1β Gene (IL1β) and one within the IL-1 receptor (IL1RN) were chosen for haplotype association with the occurrence of radiographic osteoarthritis (ROA) in the hip, knee and hand." (PMID 19751505, 2009). "The therapy with an autologous serum enriched in interleukin-1 (IL-1Ra), known as IRAP (interleukin-1 receptor antagonist protein), is a therapeutic approach used in the treatment of osteoarthritis in horses." (PMID 38133217, 2023). "For several polymorphisms in the IL1B locus, in the IL1RN VNTR and also RANK, KREMEN2 among others associations with osteoarthritis were described." (PMID 36518750, 2022).
autoimmune disease (6 papers, 2014 to 2025). A disorder resulting from loss of function or tissue destruction of an organ or multiple organs, arising from humoral or cellular immune responses of the individual to their own tissue constituents. "The majority of the studies relating IL-1RN gene polymorphisms to disease susceptibility have dealt with patients with autoimmune diseases or disorders associated with chronic inflammation." (PMID 25328514, 2014). "Notably, the transcription factor nuclear factor-κB (NF-κB), a central pro-inflammatory mediator, and polymorphisms in the interleukin-1 receptor antagonist (IL-1Rα) are involved in both autoimmune diseases and leukemogenesis." (PMID 36980546, 2023). "IL1RN is known for its protective role in many autoimmune diseases." (PMID 40979590, 2025). "Therefore, a complex set of aberrant microbiota may affect the (mucosal) immune response and contribute to the autoimmune disease in IL1rn−/− mice." (PMID 28645307, 2017). "If the role of CNVs on IL1RN concerning the occurrence of IRAE during immunotherapy is not yet fully understood, IL1RN is known for its role in the development of autoimmune diseases." (PMID 35053465, 2022).
ischemic stroke (6 papers, 2015 to 2026). A stroke disorder caused by obstruction of blood flow to the brain, due to thrombotic (local blood clot formation) or embolic (due to a blood clot or other material traveling from another site) event. "Our study attempts to explain the role of the genetic variants of IL1B (C(-31)T)and IL1RN, considered to be key factors regulating inflammatory processes in the development of ischemic stroke." (PMID 31480765, 2019). "These in silico findings propose that the putative effects of ketamine on comorbid ischemic stroke and depression may involve modulation of multiple pathways, with IL1RN and DDIT3 as potential key contributors." (PMID 41849332, 2026). "Interleukin-1 receptor antagonist (IL-1Ra), an endogenous anti-inflammatory cytokine, may have several potential links to free fatty acids (FFAs) in ischemic stroke pathogenesis." (PMID 41301455, 2025). "Also, many genes encoding chemokines, cytokines and chemokine receptors, which are involved in neuroinflammatory processes in ischemic stroke, were regulated, including Cxcr2 in endothelial cells, Ccl5, Il11 and Il6 in pericytes, Lcn2 in astrocytes and pericytes, and Il1rn in microglia." (PMID 35752654, 2022).
lung carcinoma (6 papers, 2018 to 2024). "Single nucleotide polymorphisms (SNPs) in several cytokines, such as IL1B, IL-1RN, and IL-10, exhibited significant correlations with fatigue levels in survivors of lung cancer." (PMID 39564104, 2024). "IL1RN polymorphism has been reported to promote the development of lung cancer through inflammatory response." (PMID 33247170, 2020). "Marked changes in gene expression were measured for Ccl2, Ccl7, Ccl17, Ccl22, Ccl3, Ccl4, Il-1α, Il-1ß, and Il-1rn (inflammation), Lpo and Noxo1 (oxidative stress), and Mmp12 (inflammation/lung cancer)." (PMID 29463257, 2018).
Stroke (6 papers, 2011 to 2024). Sudden impairment of blood flow to a part of the brain due to occlusion or rupture of an artery to the brain. "In a study of 39 stroke patients, the presence of a C allele at a SNP located in the promoter region of IL1RN was related to the severity of post-stroke fatigue." (PMID 28109186, 2017). "In contrast some studies, have reported an association of the IL1RN with stroke." (PMID 31480765, 2019). "Female MMP-3 KO stroke brains also had decreased expression of blood cell adhesion genes Pecam1 and Icam2, and decreased expression of inflammatory response genes Ccr1, Cxcl1, Mmp9, Il4ra, Il6, and Il1rn." (PMID 39000490, 2024). "As the meta-analysis conducted in 2015 covered various stroke types, the association of IL-1RN VNTR polymorphism and IS risk was still not clarified." (PMID 30075593, 2018).